LHX9 (LIM homeobox 9)
Diseases named in the same sentence as LHX9 in open-access papers:
LHX9 is named in the same sentence as 34 diseases in open-access papers, as found by Europe PMC text mining. Sharing a sentence is not in itself a finding about the gene and the disease. The quoted sentences say what the papers report.
glioma (6 papers, 2015 to 2024). A benign or malignant brain and spinal cord tumor that arises from glial cells (astrocytes, oligodendrocytes, ependymal cells). "LHX9 expression levels are significantly reduced in human glioma tissues and are associated with poor survival in glioma patients." (PMID 38786726, 2024). "An important finding of this study is that LHX9 overexpression inhibits the colony-forming ability of glioma cells on soft agar." (PMID 34536269, 2021). "The results showed that upregulating the expression of LHX9 in glioma cells not only inhibited the growth of cells in liquid medium but also inhibited the anchorage-independent growth of glioma cells." (PMID 34536269, 2021). "By interfering with the expression of LHX9, the tumorigenicity of glioma cells was promoted, an outcome blocked by further interference with PGK1 expression." (PMID 34536269, 2021). "In this study, we investigated novel functions of LHX9 in gliomas and LHX9 regulation of PGK1 and glycolysis." (PMID 34536269, 2021). "Previous studies have shown that the expression of LHX9 significantly inhibits the migration and invasion of glioma cells." (PMID 34536269, 2021). "To investigate the functions of LHX9 in glioma cells, we overexpressed flag-tagged LHX9 (Flag-LHX9) in glioma cells and measured the effect of LHX9 expression on the growth of glioma cells using MMT and soft agar assays." (PMID 34536269, 2021). "To investigate the mechanism by which LHX9 regulates the growth and colony formation of glioma cells, we analyzed the interactions between LHX9 and a series of proteins involved in cell growth regulation." (PMID 34536269, 2021). "The experimental results showed that downregulating the expression of LHX9 in SK-N-SH and A172 glioma cells accelerated the growth of the cells in liquid medium and colony formation on soft agar." (PMID 34536269, 2021). "Restoration of LHX9 expression inhibited glioma cell migration and invasion, suggesting the implication of LHX9 on the migratory phenotype of cancer." (PMID 26099202, 2015). "It has been reported that LHX9 expression was reduced by promoter hypermethylation in malignant childhood gliomas." (PMID 26099202, 2015). "Mechanically speaking, in glioma, LHX9 was found to negatively interact with phosphoglycerate kinase 1 (PGK1), which dominates in the aerobic glycolysis pathway; while in gastric cancer, it mainly activates pyruvate kinase M2 (PKM2) to promote tumor progression." (PMID 38902711, 2024). "Additionally, studies found that LHX9 is often silenced by hypermethylation in follicular lymphoma and child glioma." (PMID 38902711, 2024). "In addition, LHX9 is demonstrated to orchestrate the reprogramming of glycolytic metabolism in gastric cancer and glioma, while simultaneously exerting a pivotal influence on the intricate regulation of cell differentiation in neural cells." (PMID 38902711, 2024). "In glioma tissues, LHX9 expression levels are significantly reduced." (PMID 34536269, 2021). "In this study, we found that the transcription factor LHX9 was downregulated in gliomas." (PMID 34536269, 2021). "We knocked down the expression of LHX9 in SK-N-SH and A172 glioma cells." (PMID 34536269, 2021). "In conclusion, we have revealed the molecular mechanism of glioma inhibition by LHX9 in this study." (PMID 34536269, 2021).
glioma (continued). "In addition, we also observed that LHX9 inhibited the colony formation of glioma cells on soft agar, suggesting that LHX9 inhibited the anchorage-independent growth of glioma cells." (PMID 34536269, 2021). "In tumor formation experiments, we observed that interference with downstream PGK1 expression almost completely reversed the tumorigenicity caused by the downregulation of LHX9 expression, suggesting that treatment with inhibitors of PGK1 is highly likely to benefit patients with glioma." (PMID 34536269, 2021). "The experimental results showed negligible protein expression of LHX9 in most glioma tissues." (PMID 34536269, 2021). "Then, we measured the expression of LHX9 in glioma tissues and paracarcinoma tissues." (PMID 34536269, 2021). "Further literature review revealed that LHX9 is a common transcription factor in the LHX family, which can participate in the progression of osteosarcoma, glioma, and ovarian cancer, and is closely associated with the glycolytic reprogramming of glioma and ovarian cancer." (PMID 37980488, 2023). "In addition, we investigated the biological functions of endogenously expressed LHX9 in gliomas." (PMID 34536269, 2021). "LHX9 is a member of the joint LHX transcription factor family and can be involved in the metabolic reprogramming of glioma and ovarian glycolytic metabolism to influence tumor progression." (PMID 37980488, 2023). "However, other functions and mechanisms of LHX9 in glioma cells are still unknown." (PMID 34536269, 2021). "Studies have shown LHX9 methylation in approximately 88% of high-grade gliomas and approximately 29% of nondiffuse fibroblastic astrogliomas." (PMID 34536269, 2021).
osteosarcoma (5 papers, 2019 to 2023). A usually aggressive malignant bone-forming mesenchymal neoplasm, predominantly affecting adolescents and young adults. "High expression of LHX9 was associated with migration and invasion of osteosarcoma cells." (PMID 37980488, 2023). "Some scholars have found that through the FRS2/TGF−/−catenin pathway, FGF-induced LHX9 controls osteosarcoma development and migration." (PMID 36303551, 2022). "It has also been confirmed that the expression level of LHX9 was significantly up-regulated in osteosarcoma, and inhibiting LHX9 reduced the ability of cell growth and invasion." (PMID 34925434, 2021). "LHX9 is induced by FGF-signaling and has been previously studied for its role in the progression of osteosarcomas." (PMID 36920035, 2023).
gastric cancer (3 papers, 2023 to 2025). A primary or metastatic malignant neoplasm involving the stomach. "In gastric cancer cells, high expression of LHX9 is closely associated with the upregulation of genes related to glycolytic metabolism, the proliferation of gastric cancer stem cells, and poor prognosis." (PMID 37980488, 2023). "Further, extensive sample studies and validation of confirmed cases are needed to explore the molecular mechanism of LHX9 regulation of gastric cancer progression." (PMID 37980488, 2023). "Therefore, LHX9 is considered a potential marker for pathological features and prognosis of gastric cancer, guiding early detection, diagnosis, and treatment." (PMID 37980488, 2023). "In addition, the knockdown of LHX9 may be a novel strategy for treating gastric cancer, and this approach may be more effective than existing therapeutic approaches." (PMID 37980488, 2023). "In addition, it was found that high expression of LHX9 could be used as a reference marker for prognosis prediction of gastric cancer patients." (PMID 37980488, 2023). "In contrast, LIM Homeobox 9 (LHX9) activates PKM2’s catalytic function, driving metabolic reprogramming and malignant phenotypes in gastric cancer stem cells, effects that can be reversed by LHX9 knockdown." (PMID 40842995, 2025). "This study aimed to reveal the critical mediator(s) that regulate glycolytic metabolism reprogramming in gastric cancer and their underlying molecular mechanism and then explore the molecular mechanisms by which LHX9 may be involved in regulating gastric cancer (GC) progression." (PMID 37980488, 2023). "According to the results, both LHX9 and PKM2 were highly expressed in gastric cancer tissues, and LHX9 could directly bind and activate PKM2, which affected the glycolytic metabolism of gastric cancer stem cells." (PMID 37980488, 2023). "Therefore, an in-depth investigation of the regulatory mechanism of glycolytic metabolic reprogramming by LHX9 and PKM2 in gastric cancer is expected to provide new strategies and potential targets for treating gastric cancer." (PMID 37980488, 2023). "This study aimed to reveal how the transcription factor LHX9 mediates the reprogramming of glycolytic metabolism in gastric cancer stem cells through the regulation of PKM2 activity and to explore its molecular mechanism in the progression of gastric cancer." (PMID 37980488, 2023). "In addition, this study only focused on the role of transcription factor LHX9 and pyruvate kinase PKM2 while ignoring other factors that may be involved in gastric cancer progression." (PMID 37980488, 2023).
colorectal cancer (2 papers, 2019 to 2024). A primary or metastatic malignant neoplasm that affects the colon or rectum. "Following a thorough analysis and retrieval, it has been determined that NEK7 and LHX9 within Activated & resting Treg %CD4 + cell, along with DN (CD4-CD8-) %leukocyte, hold promising potential as therapeutic targets for drug treatment of colorectal cancer." (PMID 38902711, 2024). "Collectively, this evidence suggests that rs17583875 may potentially play a role in colorectal cancer by regulating the expression of NEK7 and LHX9." (PMID 38902711, 2024).
malignant glioma (2 papers, 2016 to 2021). A grade III or grade IV glioma arising from the central nervous system. "Other key factors that became apparent from these GRNs include TSHZ3, previously reported to correspond to a novel potential tumor suppressor, and LHX9, which is aberrantly methylated and downregulated in malignant gliomas of childhood." (PMID 27198694, 2016). "Previous research has shown that childhood malignant gliomas involve abnormal methylation and silencing of LHX9,108 and the relationship between ISG20, CITED2, and LHX9 with OV and its molecular mechanism must be examined in depth in future studies." (PMID 34609082, 2021).
astrocytomas (1 paper, 2010). "Now, many other genes such as LHX9, MGMT, CDKN2A, PTEN, and P15 have been shown to be methylated in astrocytomas." (PMID 20334650, 2010).
autism (1 paper, 2020). Persistent deficits in social interaction and communication and interaction as well as a markedly restricted repertoire of activity and interest as well as repetitive patterns of behavior. "Transcriptome analysis showed new markedly altered genes (e.g., KLHL1, LHX9, and MGARP) and a large number of differential expression genes (DEGs), some of which are related to autism." (PMID 34567661, 2020).
depression (1 paper, 2022). "As to LHX9, the hypothalamic marker has been proven highly correlated with FOXP2 in patients with depression." (PMID 36686487, 2022).
endometriosis (1 paper, 2025). The growth of functional endometrial tissue in anatomic sites outside the uterine body. "Next, the expression and localization of LHX9 were characterized in the endometrium during proliferative and secretory phases as well as in endometriosis lesions using immunohistochemical staining." (PMID 40802848, 2025). "Moreover, LHX9 expression was significantly elevated in ectopic endometrium compared with eutopic endometrium in patients with endometriosis." (PMID 40802848, 2025).
Hydrocephalus (1 paper, 2015). Hydrocephalus is an active distension of the ventricular system of the brain resulting from inadequate passage of CSF from its point of production within the cerebral ventricles to its point of absorption into the systemic circulation. "Recent studies have shown that the Lhx9 homeobox gene controls pineal gland development and prevents postnatal hydrocephalus." (PMID 26321920, 2015).
lung carcinoma (1 paper, 2021). "LHX9 encodes a transcription factor that might involve the control of cell differentiation of several neural cell types, but its methylation status in lung cancer has not been reported." (PMID 34620221, 2021).
Parkinson disease (1 paper, 2023). A progressive degenerative disorder of the central nervous system characterized by loss of dopamine producing neurons in the substantia nigra and the presence of Lewy bodies in the substantia nigra and locus coeruleus. "We have also identified LHX9 (LIM Homeobox 9), which is a protein coding gene, and one study found LHX9 a strong candidate gene in their analysis of single cell RNA-seq on sporadic Parkinson's disease." (PMID 37654790, 2023).
tumor (9 papers, 2011 to 2025). "To explore the plausibility of these gene as carcinogenic factors, we conducted an extensive literature retrieval and found several studies providing evidence supported the association between NEK7 and LHX9 with tumor initiation and progression." (PMID 38902711, 2024). "Interfering with PGK1 restored the tumor volume and weight caused by downregulation of LHX9 expression." (PMID 34536269, 2021). "Recently, our lab found that the expression of LHX9 was up-regulated in OS tumor tissues and cells by RNA-seq and RT-qPCR analysis, but the association between OS progression and LHX9 overexpression was still elusive." (PMID 31788020, 2019). "Meanwhile, the tumor volume was smaller in nude mice transplanted with LHX9-knockdown OS cells after 4-weeks, which implicated that the growth of OS cells was dampened after LHX9 knockdown." (PMID 31788020, 2019). "The effect of the LHX9/PKM2 axis on the tumorigenic ability of GCSCs in nude mice was observed by constructing a subcutaneous transplantation tumor model." (PMID 37980488, 2023). "At first, we found that the expression level of LHX9 was significantly up-regulated in OS tumor tissues and cell lines." (PMID 31788020, 2019). "Lastly, we performed tumor metastasis assay by intravenously injection of shNC- or shLHX9-transfected 143B cells into nude mice, which was implemented to ascertain the effect of LHX9 on tumor cell metastasis." (PMID 31788020, 2019). "In accord with the in vitro data, metastatic tumor multiplicity on lung tissues derived from LHX9-knockdown cells was evidently lower than that derived from shNC-transfected cells, which meant that the metastasis of OS cells was inhibited if LHX9 was lacking." (PMID 31788020, 2019). "To confirm the conclusion obtained with patient tumor samples, we further assessed the expression of LHX9 in various OS cell lines, including 143B, U2OS, MNNG-HOS and Saos-2." (PMID 31788020, 2019). "Among malignant epithelial subpopulations, IGFBP3+Epi (IGFBP3-expressing epithelial cells) and LHX9+Epi (LHX9-expressing epithelial cells) had elevated glycolysis levels, which correlated with poor prognosis, immune suppression, and changes in the tumor microenvironment." (PMID 40115255, 2025). "The results showed that compared to the sh-NC group, the lactate and ATP contents in tumor tissues were significantly reduced in the sh-LHX9 group, and the mRNA and protein expression of glycolysis-related genes (GLUT1, HK2, LDHA, and PDK1) were also significantly reduced." (PMID 37980488, 2023). "We observed a much slower tumor growth for LHX9-knockdown OS cells." (PMID 31788020, 2019). "To confirm this finding, we then performed RT-qPCR experiments with another batch of OS tumor tissues and peritumor tissues from patients, and the data demonstrated that LHX9 expression was significantly higher in OS tissues when compared with that in normal tissues." (PMID 31788020, 2019). "LHX9 expression was evidently up-regulated in OS tumor tissues and cell lines." (PMID 31788020, 2019). "LIM Homeobox 9 (LHX9), highly expressed in GC, transcriptionally activates pyruvate kinase M2 (PKM2) to induce glycolytic reprogramming, enhancing the malignant properties of GC stem cells and driving tumor progression." (PMID 41158522, 2025). "Evidence suggesting that the expression of NEK7 and LHX9 may be potential reasons for the inverse correlation between Treg cells and CRC risks, whereas the factors for the anti-tumor effects of DN cells remains uncertain." (PMID 38902711, 2024). "At last, we compared the tumor growth and metastasis of OS to lung with or without LHX9 in vivo, the data also supported that LHX9 was required for the growth and metastasis of OS." (PMID 31788020, 2019). "In addition, three genes common to both patients which carried bivalent marks in normal and lost H3K4me3 in tumor, LHX9, PKNOX2 and LBXCOR1 and one, PRDM8, lost the H3K27me3 in tumor, all of which are transcription factors with unknown function in colon." (PMID 22011431, 2011).
cancer (6 papers, 2015 to 2025). A tumor composed of atypical neoplastic, often pleomorphic cells that invade other tissues.
cardiovascular diseases (1 paper, 2024). "Drugs targeting NEK7 exhibit the highest abundance, while LHX9 only attracts one substance named otenzepad, an acetylcholine receptor antagonist designed to treat cardiovascular diseases, which surprisingly shows effectiveness for NEK7 as well." (PMID 38902711, 2024).
heart disease (1 paper, 2018). "Multiple genes known or plausibly linked to heart development and post-natal heart disease were found to be differentially methylated in the blood DNA of newborns with TOF including: ABCB1, PPP2R5C, TLR1, SELL, SCN3A, CREM, RUNX and LHX9." (PMID 30212560, 2018).
immune dysfunction (1 paper, 2024). "By integrating the MR results, it can be inferred that the gene expression of NEK7 and LHX9 in Activated & resting Treg & CD4 + cell plays a crucial role in carcinogenesis and immune dysfunction." (PMID 38902711, 2024).
psychiatric disorder (1 paper, 2023). A disorder characterized by behavioral and/or psychological abnormalities, often accompanied by physical symptoms. "Earlier studies found the relation of LHX9 with these neurons that are relevant to psychiatric disorders." (PMID 37654790, 2023).
LHX9 also shares sentences with these, for which no sentence is quoted: follicular lymphoma (2 papers); ovarian carcinoma (2); acute lymphoblastic leukemia (1); breast carcinoma (1); cervical cancer (1); chronic myeloid leukemia (1); clear cell renal cell carcinoma (1); diabetes (1); head and neck squamous cell carcinoma (1); infection (1); Insulin resistance (1); narcolepsy (1); Nephroblastoma (1); neurodegenerative disease (1); Ovarian Insufficiency (1); thyroid cancer (1).